CD4 (CD4 molecule)
Diseases named in the same sentence as CD4 in open-access papers (continued):
Sharing a sentence is not in itself a finding about the gene and the disease.
cancer (continued). "The antigen-specific CD4+ and CD8+ T-cell responses that were originally observed in the screening with proteins extracted from primary cancer cells were further confirmed using corresponding recombinant proteins." (PMID 24432020, 2014). "There is little information on the status of naturally occurring MSLN-specific CD4+ and CD8+ T cell responses in cancer patients." (PMID 24520352, 2014). "Most of these cell lines were derived from lymphocytes from normal blood (e.g., T cells CD4+ Th0 adult, Monocytes CD14+ RO01746), while some cell lines came from cancer patients (e.g., Gliobla and HeLa-S3)." (PMID 25393678, 2014). "Baseline evidence of fully activated type I CD4+ and CD8+ antigen-specific T cell immunity against cancer-testis (NY-ESO-1) and melanocytic lineage (MART-1, gp100) antigens was detected and was significantly potentiated after ipilimumab." (PMID 24498358, 2014). "It is well known that antigen-specific CD4+ and CD8+ T cells are detected in advanced tumor stages and that adoptive T-cell transfer can be very effective in cancer therapy." (PMID 24432020, 2014). "CD4+CD25+ regulatory and CD4+CD25- effector T-cells were purified from the peripheral blood of 36 cancer patients and co-cultured in the presence of a polyclonal stimulus." (PMID 24456704, 2014). "A number of studies have identified CD4+ CD25+ Treg cells infiltration of draining lymph node in mouse models and human cancer." (PMID 24264641, 2014). "vii) In contrast, low numbers of fibroblasts (L1) were correlated with an increased percentage of Ki67+ carcinoma cells (N) as well as a high accumulation of CD3+ (A) and CD4+ (C) T cells." (PMID 24797069, 2014). "In order to reject invading pathogens and cancer cells, the concomitant activation of both CD8+ and CD4+ T cells and the selective activation of CD4+ T cells with helper function are required." (PMID 24224170, 2013). "One of the strategies, which is used in cancer immunotherapy to kill cancer cells by bio-engineered mesenchymal stem cells (MSC), is in development and can apply to eliminate quiescent memory CD4 T-cells harboring HIV." (PMID 24151495, 2013). "In general, Tregs is identified as CD4+CD25+CD127−/low or CD4+CD25+Foxp3+, which are commonly rich in primary tumors, draining lymph nodes, and peripheral blood of cancer patients." (PMID 24350284, 2013). "The mean CD4+ T-cell count in ICC has been shown to be 312/μL, showing that there is less immunosuppression in ICC than other cancers." (PMID 23882298, 2013). "Tregs have been found to directly inhibit not only CD4+ helper T cells and CD8+ cytotoxic T cells but also NK cells following cancer immunotherapy." (PMID 23874581, 2013). "Exhausted CD4 and CD8 T cells have since been described in cancer and chronic viral infections such as SIV, HIV, Hepatitis C (HCV) and Hepatitis B (HBV)." (PMID 22916009, 2012). "Elevated levels of regulatory T cells (Tregs), usually characterised as CD4+, CD25+ and/or transcription factor forkhead box P3 (FoxP3) cells, has been widely reported to prevent the immunological clearance of many types of cancer." (PMID 24213326, 2012). "In clinical practice, the CD4+/CD8+ ratio is generally used as an indicator of antitumor immunity and as a prognostic flag for cancer patients receiving immunomodulative therapy." (PMID 23139816, 2012). "Among the cancer patients an increased neutrophil/lymphocyte ratio, a low neutrophil and CD14high CD16+ monocyte activation state and an elevated CD4/CD8 ratio were related to poor survival." (PMID 23251433, 2012). "To investigate this aspect, we focused our attention on CD4+CD25+ regulatory T cells, which turn out to be the main mediators of active immune escape in cancer." (PMID 22359669, 2012). "The ratio of CD4+CD25+high to CD4+ was 3.58 ± 3.19 % in normal adults and 6.01 ± 5.89 % to 13.50 ± 23.60 % in different kinds of malignancies (p < 0.001)." (PMID 22722448, 2012).
cancer (continued). "Recent studies demonstrated that functionally competent CD4+ and CD8+ T cells with specificity for cancer antigens are spontaneously induced in the bone marrow of all PC patients." (PMID 22110523, 2011). "This is of particular importance when only using CD4 and CD25 for the identification of Treg cells in cancer patients, as contamination with effector T cells most frequently occurs when solely these two markers are used for analysis." (PMID 21904560, 2011). "Except cancer cells, the VEGFR2 protein has been recently shown to be expressed selectively on a subset of T cells, namely, the CD4+ FoxP3+ Tregs." (PMID 21318181, 2010). "CD4+CD25+ Treg cells repress inflammation, but have been found to be elevated in several different human cancers, and suppress immune responses." (PMID 20017942, 2009). "We also showed that T cells adjacent to cancer cells express CXCL16/CXCR6, that CXCL16 is produced preferentially by CD4+CXCR6+ T cells, and that CXCL16 can enhance the proliferation of T cells." (PMID 19690611, 2009). "For example, a marked increase in CD3+ and CD4+ subsets and in the CD4+/CD8+ ratio in peripheral blood of cancer patients has been observed following HIFU treatment." (PMID 17625013, 2007). "As the cancer progressed at the tongue root, the percentage of CD3+CD4+ T lymphocytes and NK cells and the levels of IFN-γ and IL-2 decreased gradually, while the percentage of CD3+CD8+ T lymphocytes and the levels of IL-4 and IL-10 increased." (PMID 17338814, 2007). "Given the emerging heterogeneity of this cell population, it is important to consider how subsets of CD4+CD25+ cells relate to other helper T cells and to disease in individuals with cancer." (PMID 15714205, 2005). "Compared with benign diseases, high levels of infiltrating CD4+ and CD8+ T cells and DCs were observed in cancer specimens." (PMID 14583778, 2003). "While the Fas/FasL pathway appears to participate in inducing apoptosis of CD4+ T cells in HIV and of CD8+ T cells in cancer, it is clearly not the only mechanism responsible for elimination of activated T cells." (PMID 12698200, 2003). "Considering that SLAMF7 is a target in cancer therapy, its epigenetic regulation in Th1 cells and differential expression in IFN‐γ producing memory CD4+ T cells encouraged us to take a closer look at the SLAMF7 expression at the protein level in TCR‐triggered CD4+ T cells." (PMID 41187703, 2026). "Notably, we found both CD4+ and CD8+ CD103+ T co-localised with CXCL10 macrophages, as was noted in other cancers, albeit at a lower spatial profiling resolution." (PMID 41542042, 2026). "A previous study has demonstrated that Tregs can selectively induce the apoptosis of CD8+ T cells but not CD4+ T cells in the context of certain cancers such as HNSCC." (PMID 41596443, 2026). "From the clinical point of view, Tαβ CD4+CD8lo cells have been found to be expanded in response to CMV, as well as in different types of cancer, including CLL, which strongly supports its potential role in anti-tumoral immunosurveillance against HLA-II+ cells, like CLL cells." (PMID 39941719, 2025). "Moreover, in IDC paths #1 and #2, marker genes for endothelial cells (VWF and PECAM1), lymphocytes (CD4), macrophages (CD68), chemokines (CXCL12 and CCL5), and chemokine receptors (CXCR4) were expressed highly at the intermediate stages of cancer progression." (PMID 39965034, 2025). "Evidence suggests that after taking G. lucidum-related products such as Lingzhi capsules, G. lucidum extract, or G. lucidum spore powder supplements, there are changes in NK cell activity and CD4/CD8 ratio, indicating that cancer patients exhibit a series of cellular immune enhancements." (PMID 40507156, 2025). "To test this hypothesis, we examined the correlation between baseline GITR expression levels on CD3+, CD4+, and CD8+ T cells (D0) and the cytotoxic activity of WIOG-expanded TILs on day 14 (D14) against autologous primary cancer cells." (PMID 41280919, 2025).
cancer (continued). "The analysis identified T cell CD4+ as the most notable immune cell type correlated with CENPA; Th2 cells were positively correlated with CENPA across all cancer types, and Th1 cells were positively correlated in the majority of cancers." (PMID 39820192, 2025). "As far as the EPIC algorithm is concerned, the infiltration scores of the eight immune cells included in the comparison, that is, B cells, CAFs, CD4_T cells, CD8_T cells, Endothelial, Macrophages, NK cells, and other Cells, were significantly correlated with IFI30 in 43 cancer species." (PMID 39925804, 2025). "CD4 T cells recognize antigens presented by MHC-II, and while MHC-II expression is typically restricted to professional APCs and some subsets of CAFs, in settings of high IFN-γ, it can also be expressed by other cell types, including cancer cells." (PMID 40299790, 2025). "This dual activation of CD4+ and CD8+ T-cells in response to HER2-derived peptides underscores AE37’s potential as a therapeutic vaccine candidate, particularly for HER2-positive cancers, including breast cancer." (PMID 40333213, 2025). "Although TSLP-stimulated CD4+ Th2 cells are not cytotoxic themselves, they recruit a broad repertoire of immune effector cells to attack the cancer more effectively." (PMID 39782693, 2025). "Our study demonstrates a CD4+ T cell–specific role of GSDMD in antitumor immunity, independent of its canonical function in pyroptosis, which may raise a new perspective for cancer immunotherapy." (PMID 40759573, 2025). "Based on different surface antigens, primary CD4+ T cells can differentiate into T helper cells (Th) and regulatory T cells (Treg), while primary CD8+ T cells can evolve into CTLs in response to various cellular and molecular stimuli within cancer niches." (PMID 39744225, 2025). "Although differentiation into CD4+ and CD8+ T-cell lineages is considered irreversible, the cellular states within a cell type exhibit high plasticity, which complicates the understanding of the immune cell landscape in cancer." (PMID 40940908, 2025). "No clear correlation was observed between the frequency of CD4-Exh and CD4-Naive cells across cancer subtypes, suggesting that the CD4+T cell composition remains relatively consistent in ER,HER2,and ER_LN subtypes." (PMID 41394809, 2025). "Therefore, although they express MHC-II molecules, MHC-II+ cancer cells lack CD86 expression (P < 0.001), rendering them incapable of effectively activating CD4+ T cells." (PMID 41281745, 2025). "In addition, the mRNA expression of CD8, CD4, and Foxp3 was measured with RT-qPCR to evaluate the overall T-cell infiltration in the TME of cancer tissues." (PMID 39917292, 2025). "We lacked cancer-specific information, like the presence of bone metastases, and HIV-specific information, like CD4 count, which have previously been associated with fracture risk." (PMID 41358295, 2025). "Furthermore, A decreased CD4+/CD8+ ratio often signifies an immunosuppressive state, commonly observed in cancer patients, where compromised cellular immune function diminishes the body’s ability to recognize and eliminate malignant cells." (PMID 40958865, 2025). "In contrast, the negative correlation with CD4_Tcells was more pronounced, but this negative correlation was not quite noticeable at the pan-cancer level." (PMID 39925804, 2025). "Nevertheless, in the context of tumors, HOPX might facilitate the rapid enrichment of CD8+ T cells, neoantigen-reactive CD4+ T cells, and possibly their corresponding receptors within the TME, which in turn boosts the immune system to combat cancer." (PMID 41227363, 2025). "The CD4/CD8 ratio was 0.98 ± 0.31 in COP and 0.84 ± 0.22 in malignancies." (PMID 39860323, 2025). "After the successful use of mRNA based vaccines during COVID-19 pandemic, and considering rapid production, scalability and ability to elicit both CD4+ and CD8+ T cell responses, mRNA based vaccine approaches for cancer immunoprevention has become an active area of investigation." (PMID 40437549, 2025).
cancer (continued). "Unlike early computational models, which oversimplified immune responses, AI-driven frameworks incorporate key players such as regulatory T cells (CD4+CD25+), antigen-presenting cells (APCs), and cytokine networks, offering a comprehensive perspective on immune dynamics in cancer." (PMID 40756816, 2025). "Of note, TB is not expressed by MC38.OVA cancer cells, however according to previous studies, presentation of the immunodominant TB peptide by APCs enables CD4+ T cell helper function." (PMID 40216735, 2025). "On the basis of the expression of canonical marker genes, the 22 clusters were further annotated into 12 cell types: B cells, plasma cells, CD4+ T cells, CD8+ T cells, NK cells, NK-T cells, monocytes, dendritic cells, macrophages, fibroblasts, endothelial cells, and epithelial/cancer cells." (PMID 41425595, 2025). "For example, a clinical trial of pembrolizumab and another trial of durvalumab in patients with HIV on anti-retroviral therapy and advanced-stage cancer, reported that both therapies did not impair CD4 + cell counts or viral suppression." (PMID 40739492, 2025). "Although we were not able to investigate direct recognition of autologous cancer cells, the ability of UCPVax to trigger cytolytic CD4+ T cells suggests that they can contribute to cancer cell killing in the TME, as previously reported." (PMID 40543509, 2025). "Lung CD8+ cells from CD4-depleted Her2 mice were also superior in killing MET-1 cancer cell lines generated from MMTV-PyMT mice that lacked HER2." (PMID 40739350, 2025). "Although AE37 is primarily designed to target CD4+ T-cells, studies have demonstrated its ability to also activate CD8+ T-cells, resulting in a more comprehensive and potent immune response against HER2-expressing cancer cells." (PMID 40333213, 2025). "Our analysis revealed a negative correlation between RBP4 expression and CD4+ Th2 cell infiltration in several cancers from the TCGA database." (PMID 40004479, 2025). "Interestingly, cell-free PDSs boosted the frequency of CD69+ T cells in both strongly activated CD4+ and CD8+ populations, and the frequencies were even higher in co-cultures with cancer cells." (PMID 40240529, 2025). "On the one hand, CD4+ T cells, CD8+ T cells, and activated NK cells play crucial roles in the TME, and they are essential for orchestrating immune responses and can promote immunity, influencing the efficiency of cancer immunotherapy." (PMID 40642086, 2025). "Therefore, further investigation with large-scale cohort studies across the diverse types of irAEs, cancers, and regimens will be necessary to validate the importance of ICOS+CD4+ T cells and CXCL13 in irAE development." (PMID 40198121, 2025). "Cancer immunotherapy approaches target signaling pathways that are highly synonymous between CD4 and CD8 T-cell subsets and, therefore, often stimulate nonspecific lymphocyte activation, resulting in cytotoxicity to otherwise healthy tissue." (PMID 40761790, 2025). "We further divided cancer cells into six subsets, fibroblasts into six subsets, and immune cells into monocytes (Cd14+ monocytes, M1 macrophages, M2 macrophages, and DCs) and T cells (CD8+ T cells, CD4+ T cells, Dnajb1 high cells, and Dnajb1 low cells)." (PMID 39840525, 2025). "In the gene co‐expression network, we observed that YRDC was associated with the expression of multiple immune cell signature genes at the pan‐cancer level, including T‐cell signature genes (CD3D, CD4, CD8A, CD8B), B‐cell signature genes (CD19, MS4A1), and multiple immunoglobulin genes." (PMID 40898423, 2025). "This signature, the Grog T regulatory CD4 signature (Grog.Treg.1), did not correlate with higher performance within any of the cancer types it was derived from." (PMID 40773142, 2025). "In cancer types such as LUAD, LGG, SARC, KIRP, MESO, DLBC, BRCA-Luminal, READ, SKCM-Metastasis, OV, ACC, SKCM, CHOL, UCS, PAAD, and SKCM-Primary, ADM illustrated strong positive correlations with B cells, CD4+ T cells, and macrophages." (PMID 40529377, 2025).